PCNT (pericentrin)
Diseases named in the same sentence as PCNT in open-access papers (continued):
Sharing a sentence is not in itself a finding about the gene and the disease.
atherosclerosis (1 paper, 2023). A disease characterized by the build-up of fatty material and calcium deposition in the arterial wall resulting in partial or complete occlusion of the arterial lumen. "Given that the mechanistic pathway identified here to drive augmented atherosclerosis with pericentrin loss is dependent on SMC cholesterol biosynthesis, statins provide a targeted therapy to block the pathway specifically in patients with MOPDII." (PMID 37937642, 2023).
Caroli disease (1 paper, 2016). Caroli disease (CD) is a rare congenital liver disease characterized by non-obstructive cystic dilatations of the intra-hepatic and rarely extra-hepatic bile ducts. "In this context, we note that ATR-, PCNT- and ORC1-deficient patients display skeletal abnormalities, and there is mounting evidence that cilia function during skeletogenesis, and at least one ATR-SS patient, has been described with multiple liver cysts indicative of Caroli's disease." (PMID 26908596, 2016).
depression (1 paper, 2013). "Two further molecules regulating neurogenesis have been found to be altered in depression: pericentrin 2 (PCNT2) and epithelial membrane protein 1 (EMP1)." (PMID 23384232, 2013).
dyslipidemia (1 paper, 2015). "Major mutations in the PCNT gene in humans also affect adipocyte differentiation and can result in dyslipidemia as part of a wider insulin resistance syndrome." (PMID 26703584, 2015).
glioblastoma (1 paper, 2023). The most malignant astrocytic tumor (WHO grade IV). "Following drug exposures, glioblastoma cells were immunostained for α-tubulin and pericentrin and counterstained with DAPI." (PMID 37508338, 2023). "Here, we expressed wild-type (WT) and kinase-dead (KD) FLAG-tagged ILK constructs in glioblastoma and immunostained cells for pericentrin and FLAG." (PMID 37508338, 2023).
Hypoglycemia (1 paper, 2010). A decreased concentration of glucose in the blood. "The GTT administered to the mice transplanted with pericentrin-depleted islets showed hypoglycemia after overnight fasting (time 0)." (PMID 20676397, 2010). "Mice transplanted with pericentrin-depleted islets exhibited abnormal fasting hypoglycemia and inability to regulate blood glucose normally during a glucose challenge, which is consistent with our in vitro data." (PMID 20676397, 2010).
insulinoma (1 paper, 2010). "Association of pericentrin with insulin granules from mouse insulinoma cells was also observed by immunofluorescence of purified granules and by Western analyses of post-nuclear supernatant fractions (excluding DNA and centrosomes) derived from iodixinol density gradients." (PMID 20676397, 2010). "Our data show that in MIN6 insulinoma cells, overexpression of pericentrin causes an increase in centrosome size, which could be similar to the PCM “cloud” observed in CHO cells." (PMID 20676397, 2010). "In this study we show that pericentrin is expressed in primary mouse pancreatic islets and insulinoma cells." (PMID 20676397, 2010). "To examine the significance of pericentrin depletion in vivo we transplanted freshly isolated mouse pancreatic islets (or insulinoma cells) transduced with pericentrin or scrambled shRNA into streptozotocin (STZ)-induced diabetic mice." (PMID 20676397, 2010). "After glucose challenge, mice with pericentrin-depleted cells (both islets and insulinoma cells) initially had higher blood glucose levels (time 15 min)." (PMID 20676397, 2010). "Western analyses demonstrated pericentrin depletion in insulinoma cells using siRNAs targeting three distinct regions of pericentrin." (PMID 20676397, 2010). "For these studies we utilized insulinoma cells co-expressing control or pericentrin shRNAs and a transduction marker (GFP)." (PMID 20676397, 2010). "Both scrambled and pericentrin shRNA-transduced pancreatic islets or insulinoma cells restored normal blood glucose." (PMID 20676397, 2010). "To gain insight into pericentrin function in differentiated secretory cells, we first analyzed its expression in mouse primary pancreatic islets, as well as transformed mouse insulinoma (MIN6), and NIH 3T3 fibroblast cells." (PMID 20676397, 2010). "In mouse insulinoma cells pericentrin co-localized with insulin staining granules along the plasma membrane as shown by single z-sections taken at the ‘top’ and through the middle of the insulinoma cells." (PMID 20676397, 2010). "The shorter fasting time may explain the failure to observe a difference with pericentrin depletion at time 0 in insulinoma cells, as was observed in the islet transplanted mice fasted overnight." (PMID 20676397, 2010). "However, similar to the islet transplanted mice, plasma insulin levels were higher in mice transplanted with pericentrin depleted insulinoma cells compared to control mice, although the increase was not statistically significant." (PMID 20676397, 2010). "By 120 min, however, blood glucose levels in animals transplanted with pericentrin-depleted islets and insulinoma cells has returned to normal, suggesting that the glucose stimulated insulin biosynthesis and trafficking of granules to the membrane were not inhibited." (PMID 20676397, 2010). "To study the function of pericentrin in insulin secreting cells, we depleted pericentrin in pancreatic islets and MIN6 insulinoma cells using RNAi." (PMID 20676397, 2010). "In addition, we found that both rapidly-dividing insulinoma cells, as well as quiescent primary pancreatic islets, exhibited loss of intracellular insulin with pericentrin depletion, suggesting this phenotype was not secondary to pericentrin-dependent effects on cell cycle progression." (PMID 20676397, 2010). "In order to ensure that the observed reduction of insulin in the insulinoma cells was not due to the known effects of pericentrin depletion on cell cycle progression, we repeated our experiments in quiescent primary islets." (PMID 20676397, 2010).
leukemia (1 paper, 2024). A malignant (clonal) hematologic disorder, involving hematopoietic stem cells and characterized by the presence of primitive or atypical myeloid or lymphoid cells in the bone marrow and the blood. "In addition, we measured centrosome amplification in mitotic and interphase BALB/c splenocytes and Eμ-Ret leukemia cells, using co-staining of pericentriolar material (pericentrin), internal centriole (centrobin) and microtubules (tubulin), to define centrosomes." (PMID 38519798, 2024).
lung carcinoma (1 paper, 2015). "Future studies are required to test this possibility and others to clarify the cellular and molecular underpinnings of the disorders associated with elevated levels of pericentrin and γ-tubulin in human lung cancers." (PMID 26104890, 2015).
pancreatic cancer (1 paper, 2016). "Our data also show that Cep70 overexpression in pancreatic cancer cells results in the mislocalization of γ-tubulin and pericentrin and formation of protein aggregates." (PMID 26893288, 2016). "Our data further show that ectopic expression of Cep70 in pancreatic cancer cells results in the mislocalization of centrosomal proteins, including γ-tubulin and pericentrin, and the formation of intracellular aggregates." (PMID 26893288, 2016).
premature coronary artery disease (1 paper, 2023). "Microcephalic osteodysplastic primordial dwarfism type II (MOPDII) is caused by biallelic loss-of-function variants in pericentrin (PCNT), and premature coronary artery disease (CAD) is a complication of the syndrome." (PMID 37937642, 2023).
renal cystic disease (1 paper, 2016). "Furthermore, although PCNT and ORC1 deficiency also confer significant defects in cilia signalling, ATR-SS, MOPD-II nor MGS patients show the commonly described manifestations of defective ciliogenesis (e.g. renal cystic disease)." (PMID 26908596, 2016).
triple-negative breast carcinoma (1 paper, 2016). An invasive breast carcinoma which is negative for expression of estrogen receptor (ER), progesterone receptor (PR), and human epidermal growth factor receptor 2 (HER2). "Similar to our analysis based on pericentrin staining alone, CA defined by the overlap of pericentrin and polyglutamylated tubulin was more pronounced in triple negative breast cancer and cancers with higher histological grade." (PMID 26832928, 2016).
cancer (14 papers, 2006 to 2025). A tumor composed of atypical neoplastic, often pleomorphic cells that invade other tissues. "The paired sample analysis using TCGA database-sourced data showed the same noteworthy increase in the expressions of FAM81A and PCNT in cancers compared to paracancerous tissues." (PMID 40155922, 2025). "ABL has also been found to colocalize with pericentrin and γ-tubulin at the centrosome in cancer cells expressing GFP- and Myc-tagged ABL constructs." (PMID 37508338, 2023). "Pericentrin (PCNT), a core pericentriolar material protein during mitosis, is involved in tumorigenesis and development in various cancers." (PMID 37211383, 2023). "We also labeled tumorspheres for Sox2 (a marker for cancer stem cells), Arl13b, and pericentrin to determine if cilia are present on cancer stem cells." (PMID 32811879, 2020). "Centrosome amplification in cancer cells was examined by labeling the centrosome size with pericentrin, an oncoprotein that is localized in the pericentriolar material." (PMID 24970653, 2014). "Six additional non-synonymous SNVs were discovered and confirmed, including variants in AKAP1, PCNT and RERE, all of which have been implicated in cancer." (PMID 23803469, 2013). "In kendrin, also called "pericentrin B," overexpression was found in carcinoma cells known to have centrosomes of abnormal size and number." (PMID 23351173, 2012). "Various proteins that associate with centrosomes such as pericentrin, STK15/BTAK/Aurora-A kinase, ATR, BRCA1, BRCA2, have been shown to influence centrosome duplication in human cancer." (PMID 17081288, 2006). "Characterization of centrosome abnormalities in various cancer cell lines has revealed that supernumerary centrosomes, when devoid of centrioles, were unable to nucleate microtubules despite the presence of sufficient gamma-tubulin, pericentrin, PLK1 and AURKA proteins." (PMID 29370237, 2018). "There were significant differences in FAM81A, PCNT, and TMX4 expressions between tumor tissues and normal tissues in multiple types of cancer based on TCGA and GTEx." (PMID 40155922, 2025). "We performed KEGG pathways in the LinkedOmics database and uncovered that PCNT was involved in Cell cycle, ECM-receptor interaction, and other cancer-related signaling." (PMID 37211383, 2023). "To address this we first investigated the occurrence of primary cilia in cultures of wt and cancer OSE cells using IFM with antibodies against ciliary (Acet.tub, Glu.tub) and centrosomal (pericentrin, centrin) markers." (PMID 23351307, 2012). "Furthermore, since mutation of each of the five known Seckel genes, ATR, PCNT, CENPJ, CEP152 and RBBP8 (CtIP), cause genomic instability that is associated with apoptosis, it is possible that Seckel cells may not have the opportunity to accumulate cancer-causing mutations." (PMID 23166506, 2012).
tumor (11 papers, 2014 to 2025). "CEP131 is a centriolar satellite protein recruited by pericentrin and involved in cilium formation, centrosomal remodeling, and prevention of chromosomal instability in tumor cells." (PMID 31699974, 2019). "To confirm that these cells were tumor cells, we performed immunofluorescence staining for pericentrin, a centrosomal protein used to detect neoplastic cells." (PMID 25485753, 2014). "On the whole, our data suggested that PCNT may serve as an essential regulator in the tumor microenvironment, as well as a promising target for immunotherapy in HCC." (PMID 37211383, 2023). "Predictably, we found that the normally strict basal positioning of nuclei, apical positioning of intracellular vesicles and the supranuclear localisation of the Golgi resident protein ZFPL1 and the centrosome marker pericentrin in wild-type intestinal epithelia was lost in ApcMin/− tumour cells." (PMID 33335067, 2021). "We had previously scored this tumor cohort for CA by performing immunofluorescence for the bona fide centrosome markers pericentrin and polyglutamylated tubulin, and then enumerating centrosome number in a blinded fashion across at least 30 cells in each tumor." (PMID 33622270, 2021). "In addition, PCNT mRNA gradually elevated with the tumor stage and grades increased." (PMID 37211383, 2023). "Correlation analysis indicated that high PCNT protein expression correlated to a higher TNM stage, poorly-tumor differentiation, vascular invasion, higher recurrence rate, and low survival rates." (PMID 37211383, 2023). "Using double immunofluorescence, the colocalization of NANOG protein with pericentrin was identified by two independent anti-NANOG antibodies among 11 tumor and non-tumor cell lines." (PMID 32168958, 2020). "Based on this approach, we developed a pericentrin abnormality (PCAB) score, which we defined as the percentage of abnormal pericentrin stained bodies over total stained bodies in a whole section of FFPE-embedded cell line pellets or tumor sections." (PMID 29535384, 2018).
infection (2 papers, 2015 to 2024). The state of being infected such as from the introduction of a foreign agent such as serum, vaccine, antigenic substance or organism. "At 5 days post infection, 86% of the McIdas-infected cells expressed FoxJ1 and showed accumulation of multiple basal bodies, based on Pericentrin immunostaining (Fig. EV4B,C)." (PMID 39468302, 2024). "Moreover, our analysis revealed that 97% of the McIdas transduced cells were multiciliated 15 days following infection, based on acetylated α-tubulin and Pericentrin staining (Fig. EV3D,E)." (PMID 39468302, 2024). "The spatial domains separated by pericentrin are filled with a number of PCM proteins required for microtubule nucleation and anchoring, suggesting that YB-1 also regulates the microtubule nucleation and/or anchoring at PCM in response to infection at interphases." (PMID 26575487, 2015).
neurodevelopmental disorder (1 paper, 2017). A behavioral and cognitive disorder with onset during the developmental period that involves impaired or aberrant development of intellectual, motor, or social functions. "It is unknown, however, whether PCNT, Disc1, and PCM-1, act independently or in an orchestrated manner in neurodevelopmental disorders." (PMID 28125008, 2017).
neurological disorders (1 paper, 2021). "In addition to homozygous causal variants in ASPM or CENPJ, we discovered additional heterozygous modifier variants in WDR62, CEP63, RAD50 and PCNT—genes already known to be associated with neurological disorders." (PMID 34068194, 2021).
renal diseases (1 paper, 2022). "However, the specific mechanism of the role of CNN1 and PCNT in renal diseases is not well understood and still to be revealed." (PMID 36704339, 2022).
PCNT also shares sentences with these, for which no sentence is quoted: basal cell nevus syndrome (2 papers); Achalasia (1); acute myeloid leukemia (1); Alagille syndrome (1); Alzheimer disease (1); autism (1); Autosomal dominant microcephaly (1); bipolar disorder (1); blepharocheilodontic syndrome (1); Bloom syndrome (1); Coffin-Siris syndrome (1); Floating-Harbor syndrome (1); geleophysic dysplasia (1); genetic disorders (1); glioma (1); Hajdu-Cheney syndrome (1); herpesvirus infection (1); Hyperinsulinemia (1); incontinentia pigmenti (1); Joubert syndrome (1); Leber congenital amaurosis 11 (1); liver cysts (1); microphthalmia (1); Mitosis (1); morbid obesity (1); muscular dystrophy (1); osteochondrodysplasia (1); progressive myoclonic epilepsy-10 (1); respiratory diseases (1); retinoblastoma (1).
A further 11 diseases each share a sentence with PCNT in 1 paper.